CRP (C-reactive protein)
Diseases named in the same sentence as CRP in open-access papers (continued):
Sharing a sentence is not in itself a finding about the gene and the disease.
infection (continued). "Due to severe tissue damage like injury, infection or inflammation, CRP-concentration rises in a cytokine-mediated response within 24–72 h, while highest concentrations of CRP triggered by bacterial infections have been found in serum, increasing CRP values up to 1,000-fold." (PMID 39715856, 2024). "The kinetics of CRP-ratio, relative to the day of infection diagnosis, and the identification of four CRP-ratio patterns have demonstrated utility in the assessment of response to therapy in severe CAP with this ratio unaffected by intercurrent glucocorticoid therapy." (PMID 39020244, 2024). "PCT is significant in systemic or severe infections, and it increases faster than CRP." (PMID 39411281, 2024). "Children with signs of infection or elevated C-reactive protein levels were excluded." (PMID 39859969, 2024). "Elevation of CRP is used as an early marker to predict severe infection." (PMID 39341750, 2024). "The laboratory markers, like the creatinine and baseline C-reactive protein levels, although not available for all the patients, indicated rather an increased risk for infection in the early compared to the delayed patient group." (PMID 38667735, 2024). "CRP is an acute-phase reactant of proinflammatory cytokines released by the body after infection." (PMID 39507495, 2024). "Moreover, the combined use of PCT and CRP significantly enhances the sensitivity for detecting infections in febrile patients." (PMID 38956649, 2024). "More than half of the GPs mentioned that they perform a point of care test (blood sample) to measure C-reactive protein to investigate whether the patients have signs of infection in the blood." (PMID 38621790, 2024). "This could lead to difficulties regarding a clear interpretation, especially in patients with additional infections where CRP concentrations may affect therapy and prognosis." (PMID 37982862, 2024). "In addition, in our study, C-reactive protein > 8 mg/L or white blood cells counts > 10 × 109/L indicated an infection according to the reference ranges of Beijing Children’s Hospital, possibly leading to some bias in the results." (PMID 38783260, 2024). "CRP is recognized as a robust marker of acute systemic inflammation and severe infection." (PMID 39768627, 2024). "In addition, 48 or 72 h after antibiotics therapy, both the IL‐6 and CRP percentage changes showed the predictive ability of anti‐infection efficacy." (PMID 38967137, 2024). "Studies show that in patients who develop postoperative infections, CRP levels increase rapidly." (PMID 39669267, 2024). "This could be attributed to the fact that high CRP levels may reduce catheter blood flow, thereby promoting thrombus formation and subsequently increasing the infection probability." (PMID 38536779, 2024). "CRP, an acute-phase protein, serves as an early marker of infection or inflammation." (PMID 38693966, 2024). "Clinical outcomes, including Visual Analog Scale (VAS) pain scores, infection markers (C-reactive protein (CRP), erythrocyte sedimentation rate (ESR), white blood cell (WBC)), and fusion rates, were recorded preoperatively and at six weeks, three months, six months, and one year postoperatively." (PMID 39866983, 2024). "Growing evidence indicates that CRP plays a significant role in inflammation and the host response to infection, including the complement pathway, apoptosis, phagocytosis, nitric oxide release, and the release of inflammatory cytokines, particularly interleukin-6 and tumor necrosis factor-alpha." (PMID 39610974, 2024). "PIS was first characterized by Velazquez in 1990 as a condition involving postoperative fever, elevated WBC counts, and elevated CRP levels without an underlying infection." (PMID 39407997, 2024). "In this study, CRP concentration serves as an indicator of infection severity." (PMID 40046178, 2024). "PCT has been correlated with other infection/inflammation markers such as CRP and WBC count." (PMID 39305165, 2024).
infection (continued). "CRP levels were not a reliable predictor for a bacterial coinfection (OR 0.99, 95% CI 0.94–1.06, p = 0.850), while another clinical focus of infection was positively associated (OR 3.86, 95% CI 1.45–11.55, p = 0.010)." (PMID 37889376, 2024). "However, it is important to note that elevated CRP levels can sometimes play a protective role against infection by reflecting innate immune activation in response to foreign pathogens." (PMID 39458141, 2024). "This study suggests serum calprotectin, procalcitonin, and CRP may serve as valuable biomarkers to differentiate between types of infection, in addition to clinical input and decision-making." (PMID 38786153, 2024). "Further, the infection induces a complex immune response associated with the synthesis of interleukins IL-6, IL-1β, IL-1α, IL-2, IL-7, IL-8, tumor necrosis factor (TNF-α), interferon-γ (IFN-γ), and C-reactive protein (CRP)." (PMID 39329868, 2024). "Furthermore, different levels of impact were shown by CRP (Partial η2 = 0.103), followed by the highest temperature during the acute phase of infection (Partial η2 = 0.089)." (PMID 39197062, 2024). "We found PCT had a greater AUC and NPV than CRP when PCT reached a critical threshold of 1.39 ng/mL on POD 3, indicating that PCT may be a stronger predictor of infection following LGC than CRP." (PMID 38504206, 2024). "During the second round of phage therapy, the patient’s infection markers (CRP, IL-6) initially increased and then decreased, which may be related to the immune system’s response to Pseudomonas aeruginosa." (PMID 39760039, 2024). "Moreover, psychiatric medications, particularly antipsychotics, can modulate inflammatory responses, further influencing CRP levels during infection." (PMID 39408010, 2024). "In a meta-analysis of five studies (n = 678), PSP and PCT (respectively, AUROC 0.80–95%CI 0.75–0.85 and AUROC 0.79–95%CI 0.74–0.84) had a better performance than CRP (AUROC 0.56–95%CI 0.50–0.63) in discriminating mild infection from severe infection, sepsis, and septic shock." (PMID 39200255, 2024). "There is no consensus on DMD-specific proinflammatory cytokines; undoubtedly, elevated CRP may accompany infection, as in the general population, but it may also be related to excess fat." (PMID 38999890, 2024). "CRP is currently one of the most frequently used biomarkers for infection in the ED worldwide." (PMID 38254697, 2024). "It is, therefore, not surprising that patients with a combination of these factors may require a longer time to sterilise the infection and reach the established serum CRP reference range." (PMID 39766606, 2024). "The serum CRP and synovial fluid neutrophil count were found to be highly sensitive tests in detecting joint infection, as their values are rarely within the normal range in the presence of infection." (PMID 39285443, 2024). "In the correlation plots, one patient with an hs-CRP concentration above the normal reference (33 mg/L, reference < 10 mg/L) was excluded due to the possibility of this patient having an ongoing infection or acute inflammatory reaction affecting the measured biomarkers." (PMID 39000435, 2024). "The study found significant differences in CRP values on day 1 and day 3 after CC, suggesting that abnormal increases in CRP on these days may be indicative of infection." (PMID 38992621, 2024). "CRP biosensors can quickly measure C-reactive protein levels to assess inflammation or infection." (PMID 38893627, 2024). "Though the CRP and procalcitonin levels were not significantly independent risk factors for severe infection requiring amputation, their diagnostic accuracy for amputation was fair (0.7 ≤ AUC < 0.8)." (PMID 38673584, 2024). "Leukocyte, C-reactive protein, and procalcitonin can serve as indicators of infection severity." (PMID 39495969, 2024). "During the process of infection and inflammation, CRP and PCT are remarkable biomarkers." (PMID 38455656, 2024).
infection (continued). "First, CRP has been traditionally used as a marker of infection and cardiovascular events, and its elevation may reflect an aggravation of the inflammatory response in patients with HF." (PMID 38233747, 2024). "For other pathogens, peak CRP levels were higher in episodes with anaerobic and polymicrobial infections (190–200 mg/L), and the latter had the slowest recovery rate, remaining at ∼75 mg/L by day 8; recovery was also slower in Candida bloodstream infection episodes (∼60 mg/L by day 8)." (PMID 38599549, 2024). "For suspected cases of infection, even if the first-stage operation is successful, the recommended approach is to replace the cement spacer within 4 weeks, until the wound is completely healed and the serum CRP level is restored to the normal level." (PMID 38600472, 2024). "The CRP level was monitored every other day in the current cohort in order to detect infection in asymptomatic patients and to evaluate the response to antibiotic therapy in patients with severe infections." (PMID 39341750, 2024). "CRP levels might help differentiate these two conditions (mean CRP of 42 in infection in contrast to 8.8 in a flare)." (PMID 39011429, 2024). "CRP serves as a reliable marker for detecting infection issues post-colorectal surgery." (PMID 39598263, 2024). "When infection is suspected, it is advisable to perform tests for inflammatory markers and wound culture with representative inflammatory markers, including C-reactive protein (CRP), procalcitonin, and presepsin." (PMID 38673584, 2024). "In addition, CRP demonstrated predictive ability of initial antibiotics against infection at 24, 48, and 72 h after therapy, with the AUC of 0.724, 0.741, and 0.797, respectively." (PMID 38967137, 2024). "CRP trajectories significantly differ based on infection type and antibiotic treatment." (PMID 39467995, 2024). "Studies indicate that C-reactive protein (CRP) or early signs of infection can serve as predictors." (PMID 39387917, 2024). "However, due to its elevation in both situations, the CRP level lacks effectiveness in effectively distinguishing between infection and surgical complications." (PMID 38696304, 2024). "However, according to a previous report, post-ACLR infection is commonly observed between seven and 14 days postoperatively, indicating that it is too early to judge the presence of infection based on CRP levels at three days postoperatively." (PMID 39539898, 2024). "Additionally, the diagnostic efficacy of this model outperformed the currently employed clinical markers for infection, such as peripheral blood leukocyte classification, CRP and PCT, as well as comprehensive analyses combining these three indicators." (PMID 39635594, 2024). "However, an increase in procalcitonin must always be taken into account as an indicator of a possible severe infection; as such, we must also pay attention to other signs of infection in addition to an increase in procalcitonin or CRP." (PMID 39685604, 2024). "It is pertinent to note that elevated CRP values may be present in various pre-existing diseases and conditions, as well as post-operative procedures unrelated to the manifested infections." (PMID 39063921, 2024). "Moreover, CRS, fever, PCT, IL-6, and CRP emerged as potential indicators for the early detection of infections." (PMID 38956649, 2024). "Whenthe body experiences inflammation and infection, CRP levels increase." (PMID 39742221, 2024). "Elevated CRP levels serve as an indicator of increased infection risk, though they are not a definitive diagnostic tool for wound healing disorders." (PMID 39063921, 2024). "CRP is an acute-phase protein that acts as an early indicator of infection or inflammation." (PMID 39407172, 2024). "In our case, the presence of neutrophilia with a left shift and elevated levels of ferritin and CRP can indicate a strong inflammatory response in the body, which could suggest the presence of a severe infection, such as parasitic sepsis." (PMID 39598252, 2024).
infection (continued). "Repeated analysis of infective markers like WBC, ESR, and CRP was done to check whether the infection was under control." (PMID 39221359, 2024). "CRP, a commonly used marker for inflammatory response, typically rises 4–6 h after infection onset, peaks at 36–72 h, and gradually decreases 4 h after the infection is controlled." (PMID 38509094, 2024). "Consequently, monitoring the CRP concentration in urine is of significant interest for the early detection of infections and inflammatory responses." (PMID 38920587, 2024). "The cost-effectiveness of CRP POCTs compared with traditional central laboratory testing in the management of acute childhood infections in the ED is unclear and warrants further evaluation and should incorporate a range of outcomes both at the level of the individual patient and health services." (PMID 38504318, 2024). "Concerning CRP, the immunoturbidometric assays are reliable, stable, reproducible, have a rapid turnaround time, and are cheap (< 4€ in Europe), with an adequate limit of detection (0.3 to 5 mg/L) for infection management." (PMID 39020244, 2024). "CRP and procalcitonin are adjuncts used in the diagnosis of infections." (PMID 39057774, 2024). "Serum levels of C-reactive protein [37.5 (9.8, 118.0) vs. 13.5 (6.9, 33.5), p = 0.005] and erythrocyte sedimentation rate [38.0 (15.0, 63.0) vs. 22.0 (13.0, 38.5), p = 0.021] were lower in the reinfection group than in the first infection group." (PMID 38881657, 2024). "In another study of adult burn patients, plasma CRP concentrations exceeding 8 mg/dl could distinguish infection-induced inflammatory responses from other types of inflammation, indicating its potential as a predictor of infection." (PMID 39716257, 2024). "Based on these results, infection is likely in case of persistently high CRP and PCT, and antibiotic initiation may be recommended." (PMID 38279274, 2024). "Furthermore, the number of cases for which mixed anticancer agents were discarded because of infection decreased from 11 (fever: n = 8; elevated CRP or WBC: n = 3) to one (elevated CRP: n = 1) a year." (PMID 36650580, 2023). "Several studies have shown that GPS has higher prognostic power than PNI in patients undergoing dialysis; however, its application in current routine clinical practice is limited due to cost and specific clinical situations for measuring CRP (e.g., active infection status)." (PMID 36678182, 2023). "Following the onset of infection, trauma, and inflammation, storage proteins in the body such as muscles and albumin undergo degradation, leading to the enhanced production of the inflammatory protein CRP (C-reactive protein) to activate the immune response." (PMID 38137581, 2023). "The CRP serum level begins to rise between 10 and 12 h after the infection onset and peaks at 48 h." (PMID 37627653, 2023). "When infection and injury take place, CRP rises sharply in the plasma." (PMID 37996953, 2023). "Moreover, CRP plays a crucial role in response to the host’s infection through NO release, phagocytosis, apoptosis and cytokine production, particularly IL-6 and TNF-α." (PMID 37237892, 2023). "CRP is a highly sensitive biomarker for inflammation, tissue damage, and infection." (PMID 37239895, 2023). "In contrast, another study analyzed high-sensitivity C-reactive protein (hs-CRP) and procalcitonin, another marker indicating infection and systemic inflammatory status, and discovered that only the procalcitonin concentration was significantly higher in patients with SSNHL than in control subjects." (PMID 37893435, 2023). "Similarly, CRP, an acute-phase reactant that rises rapidly during inflammation and infection, was selected for its routine use in monitoring these conditions and its proposed relationship with ROP development." (PMID 37371000, 2023).
infection (continued). "Common biomarkers, such as C-reactive protein (CRP), procalcitonin (PCT), and interleukin-6 (IL-6), are generally associated with inflammation, and thus, their specificity for infection is low and could be affected by many other reasons." (PMID 37181361, 2023). "Upon infection, CRP levels increased after any protocol as expected." (PMID 36631814, 2023). "The 89.6% infection eradication rate and 81.8% success rate achieved in our study support the literature in light of available information.High levels of serum biomarkers CRP and ESR play a critical role in the preoperative diagnosis of PJI." (PMID 37637597, 2023). "In addition, CRP is an acute-phase protein produced in response to infection or damage and an inflammatory marker." (PMID 37645411, 2023). "Therefore, the association with infection is unclear given that both IL-6 and CRP are rapidly restored to the normal range once the infection is cleared." (PMID 37789021, 2023). "PCT and CRP are commonly used clinical markers of infection." (PMID 36687389, 2023). "Consequently, CRP levels demonstrated a poor specificity (37–40%) to diagnose postoperative infection in these two protocols." (PMID 36631814, 2023). "Blood PCT was 100 ng/ml and CRP 199 mg/L, indicating critical infection." (PMID 37434786, 2023). "This is of particular importance, since the clinical utility of CRP in particular in an early stage of the infection is often hampered by this area of uncertainty in which CRP offers inferior diagnostic accuracy with respect to detecting serious bacterial infections in children." (PMID 36757525, 2023). "As CRP displays the highest sensitivity among the three traditional biomarkers, it is frequently used to monitor whether infection occurs after surgery." (PMID 37153693, 2023). "In this study, the increased MPO and CRP activities in the serum of the PC group indicated that NE infection could activate immune cells in the blood and promote inflammation." (PMID 37143114, 2023). "When the change over the weeks was examined, the results showed that the CRP changed significantly in the infection group (p = 0.004) and nearly significantly in the hospital group (p = 0.063) and so did the IL4 in the healthy group (p = 0.007) and in the hospital group (p = 0.031)." (PMID 37762523, 2023). "From our point of view, the significant presence of infection in all CRP ranges is the main reason for low Kappa scores for the inter-rater agreement observed in our study between the CRP-NLR combination predicted infection and a clinical diagnosis of infection." (PMID 37016028, 2023). "As an acute phase protein, CRP is elevated in trauma as well as infection and inflammation." (PMID 37893839, 2023). "Moreover, as UTIs can present with varying clinical symptoms, understanding the connection between PCT and CRP levels and infection sites holds potential for improved patient stratification and personalized treatment approaches." (PMID 37821527, 2023). "Our model showed that occurrence of infection during the rainy season, CRP ≥5.70 mg/L and presence of fever might inform clinical decision-making for hospitalized pediatric CAP, particularly with regard to antibiotic stewardship." (PMID 37275364, 2023). "Contrastingly, patients with trajectory 3 (persistently high CRP levels) had the highest mortality rate, which could be attributed to uncontrolled infection or the persistence of inflammatory factors." (PMID 37709919, 2023). "However, Delta CRP 3 mg/dl had a good NPV for peristomal wound infection and all-cause infection as a cut-off point." (PMID 37189057, 2023). "One way in which the interaction of CRP might alter infection rates and/or survival of the parasite is through the complement pathway." (PMID 37720216, 2023). "In cases of injury, infection or inflammation, levels of CRP can rise significantly." (PMID 37623168, 2023). "The liver produces CRP in response to infection and is induced to do so by IL-6." (PMID 37876930, 2023).